UQCR10 (ubiquinol-cytochrome c reductase, complex III subunit X)
Description:
Component of the ubiquinol-cytochrome c oxidoreductase, a multisubunit transmembrane complex that is part of the mitochondrial electron transport chain which drives oxidative phosphorylation. The respiratory chain contains 3 multisubunit complexes succinate dehydrogenase (complex II, CII), ubiquinol-cytochrome c oxidoreductase (cytochrome b-c1 complex, complex III, CIII) and cytochrome c oxidase (complex IV, CIV), that cooperate to transfer electrons derived from NADH and succinate to molecular oxygen, creating an electrochemical gradient over the inner membrane that drives transmembrane transport and the ATP synthase. The cytochrome b-c1 complex catalyzes electron transfer from ubiquinol to cytochrome c, linking this redox reaction to translocation of protons across the mitochondrial inner membrane, with protons being carried across the membrane as hydrogens on the quinol. In the process called Q cycle, 2 protons are consumed from the matrix, 4 protons are released into the intermembrane space and 2 electrons are passed to cytochrome c.
Synonyms: UCRC; HSPC119; HSPC051; QCR9; UCCR7.2; HSPC151
Tractability: Small molecule: a structure with a bound ligand is known. Antibody: UniProt predicts a signal peptide or a membrane-spanning region. PROTAC: ubiquitination databases record sites on it; its protein half-life has been measured.
Target class: Enzyme
Gene: Protein-coding gene on chromosome 22 (29,767,369 to 29,770,413, forward strand). Ensembl gene ENSG00000184076.
Subcellular location: Mitochondrion inner membrane
Pathways (Reactome):
Metabolism: Complex III assembly; Respiratory electron transport
Gene Ontology:
Molecular function: protein binding; quinol-cytochrome-c reductase activity
Biological process: cellular respiration; mitochondrial electron transport, ubiquinol to cytochrome c; proton transmembrane transport
Cellular component: mitochondrial inner membrane; mitochondrion; respiratory chain complex III; membrane
Genetic constraint (gnomAD): Loss-of-function variants: 6 observed, 6.39 expected, observed/expected ratio (o/e) 0.94, 90% interval 0.51 to 1.72. That is too few expected variants to judge how well the gene tolerates losing a copy. Missense variants: 101 observed, 88.74 expected, observed/expected ratio (o/e) 1.14, 90% interval 0.97 to 1.34. Synonymous variants: 40 observed, 38.28 expected, observed/expected ratio (o/e) 1.04, 90% interval 0.81 to 1.36.
Homologues: Orthologues: chimpanzee UQCR10 (100% identical), pig UQCR10 (87% identical), mouse Uqcr10 (84% identical), guinea pig UQCR10 (83% identical), rat Uqcr10 (81% identical), rat Uqcr10-ps1 (79% identical), tropical clawed frog uqcr10 (67% identical), zebrafish uqcr10 (59% identical).
Diseases named in the same sentence as UQCR10 in open-access papers:
UQCR10 is named in the same sentence as 18 diseases in open-access papers, as found by Europe PMC text mining. Sharing a sentence is not in itself a finding about the gene and the disease. The quoted sentences say what the papers report.
Alzheimer disease (1 paper, 2022). A progressive, neurodegenerative disease characterized by loss of function and death of nerve cells in several areas of the brain leading to loss of cognitive function such as memory and language. "Interestingly, recent studies have indicated UQCR10 as playing a role in Alzheimer’s disease pathophysiology." (PMID 36499081, 2022).
chronic hepatitis B (1 paper, 2017). "Lastly, to confirm a role for UQCR10 with infection from natural hepatitis B virions, UQCR10 permanent cell lines were exposed to unmodified human serum from individuals infected with chronic hepatitis B. Low but persistent viral protein production was observed for as long as 12 splits." (PMID 28572637, 2017).
diabetes (1 paper, 2022). "In our study, 6 out of 71 differentially expressed genes had records of SNPs associated with an increased risk of diabetes, including Uqcr10 and Slc7a5." (PMID 36557283, 2022).
diabetic cardiomyopathy (1 paper, 2022). Diabetic cardiomyopathy is a disorder of the heart muscle in people with diabetes. "The pathways of neurodegeneration/multiple diseases and diabetic cardiomyopathy were also significant pathways and shared altered proteins such as Atp2a32, Uqcr10, Ndufa12, Vdac1, and Vdac3." (PMID 35565902, 2022).
hepatitis B (1 paper, 2017). "We next investigated whether HepG2 and Huh7 cell lines with permanent expression of UQCR10 protein could be infected by transgenic hepatitis B particles." (PMID 28572637, 2017).
hepatocellular carcinoma (1 paper, 2017). A malignant tumor that arises from hepatocytes. "Immuno-histochemistry confirmed these findings: UQCR10 protein expression was seen in both the cytoplasm of non-neoplastic liver tissues and in the cytoplasm of hepatocellular carcinoma, but showed low to absent expression in HepG2 and Huh7 cell lines." (PMID 28572637, 2017).
lung adenocarcinoma (1 paper, 2022). A carcinoma that arises from the lung and is characterized by the presence of malignant glandular epithelial cells. "Higher UQCR10 expression is associated with better survival times in lung adenocarcinoma and lung squamous cell carcinoma." (PMID 36499081, 2022).
Parkinson disease (1 paper, 2023). A progressive degenerative disorder of the central nervous system characterized by loss of dopamine producing neurons in the substantia nigra and the presence of Lewy bodies in the substantia nigra and locus coeruleus. "Moreover, Parkinson’s disease (NDUFA9, TUBB4B, etc.; p-value = 4.94E-21), Prion disease (UQCR10, SDHA, etc.; p-value = 4.82E-17) and Pathways of neurodegeneration - multiple diseases (UBA52, etc.; p-value = 6.44E-16) were linked to the low abundant proteins in HF." (PMID 36891514, 2023).
schizophrenia (1 paper, 2014). A major psychotic disorder characterized by abnormalities in the perception or expression of reality. "The present study aimed to investigate the relationship between the clinical features of schizophrenia, and mitochondrial complex activation, based on measurement of mRNA levels in the NDUFV1, NDUFV2, NDUFS1, and UQCR10 genes involved in the peripheral mitochondrial complex." (PMID 25713723, 2014). "As there was not a difference in the mRNA level of the UQCR10 gene (complex III) between the present study’s schizophrenic patients and controls, and the range of UQCR10 mRNA levels was excessive, we do not consider activation of mitochondrial complex III an appropriate biomarker for schizophrenia." (PMID 25713723, 2014).
neurodegenerative disease (2 papers, 2017 to 2019). A disorder of the central nervous system characterized by gradual and progressive loss of neural tissue and neurologic function. "An important property of the neurodegenerative diseases is the downregulated oxidative phosphorylation because of the dysfunctional brain mitochondria and the varied genes including UQCRC1, UQCR10, SDHB, ATP5B, ATP5C1, NFUFA1, and VDAC1." (PMID 29359159, 2017). "Multiple pathways involved in neurodegenerative diseases and oxidative phosphorylation were enriched in TPLB versus OVX groups, with the regulation of several mitochondrial proteins with gene names of Ndufa7, Uqcr10, and ATP8." (PMID 31428228, 2019).
infection (1 paper, 2017). The state of being infected such as from the introduction of a foreign agent such as serum, vaccine, antigenic substance or organism. "To directly determine a role for UQCR10 in HBV infection, we analyzed UQCR10 levels in human tissues and HepG2 and Huh7 cell lines and tested whether restoration of UQCR10 protein levels in these cell lines would make them susceptible to sustained infection." (PMID 28572637, 2017).
UQCR10 also shares sentences with these, for which no sentence is quoted: tumor (2 papers); asthma (1); lung squamous cell carcinoma (1); melanoma (1); prion disease (1); tendinopathy (1); type-2 diabetes (1).